TNF (tumor necrosis factor)
Diseases named in the same sentence as TNF in open-access papers (continued):
Sharing a sentence is not in itself a finding about the gene and the disease.
Obesity (continued). "Adipose tissue in obesity releases adipokines (like IL-6, leptin, TNF-α) that sustain systemic inflammation and can alter gut microbiota composition." (PMID 41374093, 2025). "As obesity is a state of IR, adipose tissue can secrete tumor necrosis factor (TNF‐α), interleukin‐6 (IL‐6), interleukin‐1β (IL‐1β) and other substances." (PMID 41245183, 2025). "As observed in other tissues, obesity also induces inflammation in the testes, mainly through the overexpression of TNF-α, inducible nitric oxide synthase (iNOS), and IL-1β, accompanied by the underexpression of IL-10." (PMID 40002337, 2025). "In obesity, excess adipose tissue and increased production of adipokines—such as tumor necrosis factor-alpha (TNF-α), various interleukins, and resistin—trigger a state of chronic inflammation." (PMID 40283140, 2025). "This AMPK activation has been shown to negatively regulate pro-inflammatory cytokines, including TNF-α, IL-6, and MCP-1, which are key mediators of chronic inflammation associated with obesity." (PMID 40733199, 2025). "In humans, moderate exercise reduces TNF-α in individuals with high-fat diets or obesity, decreasing low-grade chronic inflammation." (PMID 40777031, 2025). "Obesity is a state of chronic inflammation, characterized by elevated levels of circulating inflammatory factors such as TNF-α and IL-6 (Hotamislig and il, 2006)." (PMID 41278194, 2025). "TNF-α inhibits the tyrosine kinase phosphorylation of the insulin receptor, which results in IR and obesity in PCOS." (PMID 40179096, 2025). "Under ME conditions in vitro, we detected in BC cells significantly increased expression of TNFα, CCL2, IL-6 and human IL-8, well-known TLR-controlled cytokines, tightly implicated in breast tumorigenesis and the obesity-cancer link." (PMID 40868123, 2025). "TNF-α, produced in the adipose tissue, is known to represent a molecular link between obesity and insulin resistance." (PMID 40565595, 2025). "Research has demonstrated a connection between overweight and obesity and elevated levels of inflammatory markers, such as tumor necrosis factor alpha (TNF-α), interleukins (ILs) 6 and 4, leptin, and macrophage chemoattractant protein-1." (PMID 40298814, 2025). "Systemic inflammation during obesity also decreased after CT treatment, with a significant reduction in serum levels of endotoxin, interleukin-1β, and tumor necrosis factor-α." (PMID 40260376, 2025). "The common mechanisms that bromelain can interfere with are the reduction in pro-inflammatory cytokines (TNF-α, IL-1β, IL-6), which are excessively produced both in obesity (by macrophages in adipose tissue) and in other inflammatory conditions." (PMID 40943267, 2025). "Obesity-related excess adipose tissue releases pro-inflammatory cytokines, such as interleukin-6 (IL-6) and tumor necrosis factor-alpha (TNF-α)." (PMID 40565268, 2025). "The initial indication of cytokine associated with obesity was found in a study that reported heightened levels of tumor necrosis factor-alpha (TNF-α) in adipose tissue in individuals with obesity." (PMID 40519917, 2025). "Leptin, which is notoriously abundant in obesity, triggers the expression of a host of pro-inflammatory and pro-tumorigenic cytokines, notably IL-1, IL-6, and TNF-α within macrophages." (PMID 40040878, 2025). "In obesity, adipocytes produce and release a variety of inflammatory factors, such as TNF- α and IL-1β." (PMID 40428495, 2025). "TNF-α plays a central role in the pathogenesis of obesity by disrupting insulin signaling, promoting insulin resistance and metabolic dysfunction." (PMID 41011232, 2025). "Obese adipocytes secrete pro-inflammatory cytokines such as tumor necrosis factor-α (TNF-α) and interleukin-6 (IL-6), which activate the “obesity–inflammation–aromatase axis”." (PMID 41157306, 2025).
Obesity (continued). "Insulin resistance itself enhances lipolysis and FFA release, and elevated FFAs in obesity activate toll-like receptors (TLRs) on immune cells, triggering inflammatory pathways like NF-κB, which increases TNF-α production." (PMID 40700071, 2025). "In obesity, vWAT undergoes pathological expansion and becomes a significant source of inflammatory cytokines, including tumor necrosis factor-alpha (TNF-α) and interleukin-6 (IL-6), exacerbating systemic insulin resistance." (PMID 40699742, 2025). "Moreover, the association between carnitine and obesity may also involve pathways of oxidative stress (e.g., inhibition of NF-κB expression) and chronic low-grade inflammation (e.g., decreased levels of IL-6, TNF-α, and CRP), which are hallmarks of obesity." (PMID 41291687, 2025). "Adipose tissue, particularly in obesity, overexpresses TNFα due to macrophage accumulation, creating an “anti-TNFα sink” analogous to ASUC." (PMID 41302991, 2025). "TNF-α and IL-6 are known to possess inflammatory properties and can induce insulin resistance, serving as significant links between obesity, diabetes, and chronic inflammation." (PMID 40225013, 2025). "TNF-α is a cytokine primarily secreted by activated macrophages, as well as by adipocytes in the context of obesity." (PMID 40722699, 2025). "Among these immune cells infiltrating AT, macrophages are the most abundant and serve as key mediators of obesity-induced inflammation through the secretion of pro-inflammatory cytokines, such as interleukin-6 (IL-6) and tumor necrosis factor- α (TNF-α)." (PMID 41432903, 2025). "This cluster also showed an enrichment of the TNF-α pathway, which aligns with the role of inflammatory cytokines in obesity-related insulin resistance." (PMID 39859351, 2025). "Serum Wnt5a, leptin, and TNF-α showed significantly higher levels in females with obesity than controls and a significant increase with higher classes of obesity." (PMID 39837875, 2025). "The results of network molecular pharmacology indicated that IL‐6 and TNF‐α were key targets for ECT in regulating obesity." (PMID 40772014, 2025). "In obesity-related insulin resistance, hypertrophic adipocytes secrete elevated levels of pro-inflammatory cytokines, such as tumor necrosis factor-alpha (TNF-α) and interleukin-6 (IL-6)." (PMID 39940428, 2025). "Curcumin reduces the production of pro-inflammatory cytokines, such as TNF-α and IL-6, which are central to the pathophysiology of diabetes and obesity." (PMID 40918536, 2025). "Obesity induces chronic inflammation primarily through the secretion of pro-inflammatory cytokines, such as IL-6 and TNF-α, and the accumulation of macrophages in adipose tissue." (PMID 40871683, 2025). "miR-146a displayed context-specific changes, where it is increased in obesity, but reduced or mixed in prediabetes, suggesting stage-dependent modulation of inflammatory signaling through IL-6 and TNFα." (PMID 41400625, 2025). "These include cytokines crucial in the pathophysiology of obesity, such as tumor necrosis factor alpha (TNF-α), interleukin-6 (IL-6), and interleukin-1β (IL-1β), thus perpetuating the chronic low-grade inflammatory state." (PMID 41153608, 2025). "In obesity, where TNF-α is chronically elevated, signaling predominantly favors sustained canonical NF-κB pathway activation, driving persistent inflammation and contributing to metabolic dysfunction." (PMID 41463063, 2025). "The main inflammatory players in obesity are pro-inflammatory cytokines such as TNF-α, IL-6, and C-Reactive Protein (CRP), as well as adipokines such as leptin, adiponectin, resistin, among others secreted by adipose tissue." (PMID 41373779, 2025). "It is an important phenotype of obesity characterized by increased levels of proinflammatory cytokines, such as TNF‐α, IFN‐γ, IL‐1β, and IL‐6." (PMID 39968210, 2025).
Obesity (continued). "Overall, a lower number of studies are currently available discussing the impact of obesity on anti‐IL‐17 or anti‐IL‐23 with respect to TNF inhibitors, and the differences in response between obese and nonobese patients resulted less prominent." (PMID 39760506, 2025). "Overall, an increase in TNF-α impaired the stability of IGF2BP3-dependent CLDN11 mRNA in obesity-related SAP, aggravating intestinal permeability and pancreatic inflammation." (PMID 39856555, 2025). "Compared to the control group, individuals with obesity showed significantly elevated levels of TNF-α and SDH, along with evidence of oxidative stress." (PMID 41334630, 2025). "Obesity is characterized by chronic low-grade inflammation driven by excessive adipose tissue, which secretes pro-inflammatory cytokines such as TNF-α and IL-6, thereby impairing insulin signaling and inducing insulin resistance." (PMID 41153828, 2025). "When there is an increase in systemic TNF- α and other proinflammatory cytokines owing to obesity, IKK, p38 MAPK, JNK, and PKC proteins are activated." (PMID 40108925, 2025). "On meta-regression, obesity and smoking were associated with increased risk of VTE with JAK inhibitors vs TNF antagonists (eTable 4 in Supplement 1)." (PMID 40928778, 2025). "The authors of a 2024 meta-analysis of 44 randomised controlled trials concluded that, compared to other diets, the KD lowers levels of inflammatory markers, such as TNF-α (WMD: −0.32 pg/mL) and IL-6 (WMD: −0.27 pg/mL) (which are associated with obesity)." (PMID 40289934, 2025). "Obesity is associated with low-grade inflammation of WAT and infiltration of pro-inflammatory M1 macrophages and increased tumor necrosis factor alpha (TNF-α) and interleukin 6 (IL-6) expression." (PMID 40522819, 2025). "TNF-alpha is a pro-inflammatory cytokine that significantly influences insulin resistance and obesity-related signaling pathways." (PMID 39762333, 2025). "Both IL-6 and TNF-α are elevated in obesity and metabolic syndrome and can induce insulin resistance by disrupting insulin signaling pathways." (PMID 40722699, 2025). "Overall, increased TNF‐α production in adipose tissue is strongly correlated with obesity‐related insulin resistance and chronic inflammation in T2DM." (PMID 39355932, 2025). "It was found that placental macrophages increased 2–3 times in mothers who have obesity, with an increase in cytokines such as IL-1, IL-6, TNF-α, and mRNA and protein expression." (PMID 40278381, 2025). "In obesity, pro-inflammatory adipokines such as tumor necrosis factor (TNF) and interleukin-6 (IL-6) are upregulated in adipose tissue, triggering chronic low-grade inflammation that impairs systemic metabolic regulation." (PMID 40703156, 2025). "Obesity is associated with a chronic low-grade inflammation, and inflammatory markers related to obesity include TNF-α, IL-6 [24,26,27,], and the anti-inflammatory cytokine IL-10." (PMID 40125475, 2025). "Moreover, COPD and obesity are associated with chronic airway inflammation and impaired interferon-mediated immunity, which may amplify cytokine production (notably IL-6, TNF-α, and IL-8), worsening pulmonary injury and contributing to acute respiratory distress." (PMID 41488075, 2025). "Most obesity-induced cytokines decrease tissue sensitivity to insulin by activating self-perpetuating cycles involving tumor necrosis factor-alpha (TNFα) and nuclear factor kappa B (NF-κB)." (PMID 41010061, 2025). "In the case of aP2/FABP4 KO male mice, the uncoupling of obesity from insulin resistance was attributed to a marked decrease in TNF-α expression in adipose tissue." (PMID 37961647, 2025). "Concentrations of adipokines have been assessed in ovarian follicular fluid, and levels of TNF-α, leptin, IL-18, and IL-10 appear to be correlated with BMI, suggesting follicular fluid-specific effects of obesity." (PMID 40755647, 2025).
Obesity (continued). "Emerging research points to shared mechanisms among IBS, obesity, T2D, and cancer, with chronic inflammation as a unifying theme: IBS involves mucosal immune activation, while obesity and T2D are marked by elevated cytokines such as TNF-α and IL-6." (PMID 41514860, 2025). "Chronic low-grade inflammation is a hallmark of prediabetes and obesity, typically characterized by elevated levels of hs-CRP, IL-6, and TNF-α." (PMID 41228432, 2025). "Obesity-related low-grade inflammatory state can alter the pharmacokinetics of anti-TNF agents, leading to reduced drug concentrations and shorter half-life." (PMID 41266905, 2025). "Increased levels of TNF-α and IL-6 in obesity contribute to systemic inflammation, insulin resistance, and the progression of metabolic syndrome." (PMID 40710568, 2025). "In contrast, obesity induces a phenotypic switch toward the pro-inflammatory M1 subtype, characterized by the release of TNF-α, IL-6, and IL-1β, which exacerbates adipose inflammation and contributes to systemic insulin resistance." (PMID 41310829, 2025). "Obesity acts as a critical mediator in this process: Visceral adipose tissue secretes free fatty acids and pro-inflammatory cytokines (such as IL-6 and TNF-α), which not only exacerbate hepatic IR but also impair renal urate excretion." (PMID 41356818, 2025). "In cancer, obesity-induced expression of growth factors, inflammatory cytokines (e.g., IL-6 and TNF-α), and adipokines (e.g., leptin) can induce dysregulation PI3K/AKT/mTOR signaling pathway, to induce cancer progression and predict a poor prognosis." (PMID 40863244, 2025). "Inflammatory macrophages produce tumor necrosis factor (TNF), a multifunctional cytokine that plays an important role in obesity‐associated chronic inflammation." (PMID 38874196, 2025). "Our results conflict with studies reporting positive correlations between obesity and IL-6/TNF-α in schizophrenia." (PMID 40791199, 2025). "Obesity-related adipose tissue secrets pro-inflammatory cytokines such as tumor necrosis factor-alpha (TNF-α), interleukin-6 (IL-6), and C-reactive protein (CRP)." (PMID 40981180, 2025). "This disruption primarily stems from chronic low-grade inflammation within adipose tissue in obesity, marked by the release of inflammatory cytokines such as TNF-α and IL-639." (PMID 40596724, 2025). "Their role in local inflammation as compared to WAT is less pronounced, although enhanced production of TNF-a and MCP-1 is caused due to obesity-related metabolic derangement." (PMID 41227378, 2025). "Elevated circulating levels of TNF‐α in both obese rodents and humans suggest a potential relationship between obesity and tumorigenesis." (PMID 40620232, 2025). "Lastly, we wanted to see if the treatment class, disease duration, obesity, alcohol consumption, smoking habit, or gender has an effect on serum levels of TNF-α, IL-17A, IL-17F, and IL-12/23 at the onset of treatment or after 12 weeks." (PMID 40699767, 2025). "Both CD4+ and CD4− iNKT subsets exhibited impaired IFN-γ production, while obesity tends to predominantly affect TNF-α production in the CD4− subset." (PMID 41000378, 2025). "Cetilistat, a next-generation lipase inhibitor, shows comparable weight loss to orlistat (−4.1% vs. −3.9%) with superior tolerability and greater reductions in TNF-α, positioning it as a potential first-line option for obesity-related intestinal inflammation." (PMID 40699756, 2025). "Several inflammatory mediators such as Interleukin (IL)-6, tumor necrosis factor (TNF-α), interferon (IFN-γ), and monocyte chemoattractant protein-1 (MCP-1) have been associated with obesity and asthma." (PMID 41153538, 2025). "Obesity increases TNF-α levels in multiple tissues, including the testis, where it plays a crucial role in inflammation." (PMID 40564033, 2025).
Obesity (continued). "In particular, the direct association between CAMKK1 and leptin was observed as attenuated in individuals with obesity, while the direct association between CAMKK1 and blood glucose or TNFα was strengthened in patients with T2DM." (PMID 40965347, 2025). "For instance, interleukin-6 (IL-6) and tumor necrosis factor-alpha (TNF-α) are pro-inflammatory cytokines released from PVAT in conditions such as obesity." (PMID 40642747, 2025). "Adipose tissue, rather than muscle, is considered the primary source of chronically elevated circulating IL-6 and other pro-inflammatory factors (e.g., TNF-a) levels in obesity." (PMID 40171198, 2025). "Obesity is characterized by a state of chronic low-grade inflammation, with increased levels of inflammatory cytokines such as IL-6 and TNF-α." (PMID 40034545, 2025). "Obesity and depression share a state of chronic low-grade inflammation, sustained by an overproduction of proinflammatory cytokines such as IL-1β, IL-6, and TNF-α." (PMID 41373743, 2025). "In obesity, there is an increase in pro-inflammatory cytokines, such as TNF-α, which can lead to ROS accumulation, inducing the expression of pro-oxidant enzymes (e.g., NADPH oxidase) and reducing the expression of antioxidant enzymes (e.g., catalase)." (PMID 40647324, 2025). "Inflammatory changes involving the TNF system (sTNFR1, sTRAIL) that correlate with obesity are present since childhood, indicating the need for early intervention in order to avoid cardiometabolic complications in adulthood." (PMID 40359199, 2025). "Obesity manifests as a chronic low-grade inflammation characterized by increased circulating levels of inflammatory factors such as tumor necrosis factor-α (TNF-α), interferon-γ (IFN-γ), interleukin-1β (IL-1β), and interleukin-6 (IL-6)." (PMID 40519937, 2025). "Obesity-related cytokines such as TNF-α and IL-6 stimulate tissue factor expression in endothelial cells and monocytes." (PMID 40871683, 2025). "TNF-α, which is known as a proinflammatory cytokine, performs important roles in the pathogenesis of obesity." (PMID 39762333, 2025). "In obesity, adipose tissue exhibits increased secretion of pro-inflammatory cytokines (tumor necrosis factor alpha (TNF-α), interleukins: IL-6, IL-8) and reduced release of anti-inflammatory mediators (IL-10), which lead to chronic low-grade inflammation." (PMID 41374066, 2025). "Obesity drives Th2-type (eosinophilic) or Th17-type (neutrophilic) inflammation in asthma through an imbalance between pro-inflammatory factors (leptin, TNF-α, IL-6) and anti-inflammatory factors (adiponectin) secreted by adipose tissue." (PMID 41244254, 2025). "Mechanistically, an increase in TNF-α impaired the stability of IGF2BP3-dependent CLDN11 mRNA in obesity-related SAP." (PMID 39856555, 2025). "Nevertheless, obesity was linked to heightened inflammatory responses in the GCF, marked by elevated concentrations of IL-6, TNF-α, and IL-1β." (PMID 40422620, 2025). "When the obesity group (n = 60) was classified according to the obesity class, the metaflammation markers under the study, leptin (p < 0.001), TNF-α (p = 0.007), and Wnt5a (p = 0.001), showed a significant increase with the higher obesity class." (PMID 39837875, 2025). "Aerobic exercise training effectively mitigated some of the obesity‐induced changes in the tPVAT, partially restoring the anti‐contractile response to 5‐HT and reducing circulatory leptin, TNF‐α, and malondialdehyde." (PMID 40842420, 2025). "In the state of obesity, adipose tissue, particularly visceral fat, has been shown to release pro-inflammatory cytokines, such as IL-6 and TNF-α, which can lead to the activation of a systemic, chronic, low-grade inflammatory response." (PMID 40735221, 2025). "We also found that diet-induced obesity increased the secretion of tumor necrosis factor-α (TNF-α), interleukin-6 (IL-6), and galectin-3." (PMID 40565066, 2025).